RNU6-420P (RNA, U6 small nuclear 420, pseudogene)
Gene: Small nuclear RNA gene on chromosome 4 (22,118,983 to 22,119,089, forward strand). Ensembl gene ENSG00000239001.
Homologues: Orthologues: chimpanzee U6 (100% identical), macaque U6 (93% identical). Paralogues in human: RNU6-38P (87% identical), RNU6-29P (86% identical), RNU6-1122P (85% identical), RNU6-1145P (85% identical), RNU6-15P (85% identical), RNU6-16P (85% identical), RNU6-25P (85% identical), RNU6-33P (85% identical), RNU6-378P (85% identical), RNU6-41P (85% identical), RNU6-468P (85% identical), RNU6-618P (85% identical), and 1288 more.